LGALS9 (galectin 9)
Diseases named in the same sentence as LGALS9 in open-access papers (continued):
Sharing a sentence is not in itself a finding about the gene and the disease.
tumor (continued). "As mentioned, the increased production of Galectin-9 (Gal9) molecules induces the binding of Tim-3 molecules expressed on Tim-3 expressing effector CD8 + T cells in the tumor microenvironment, which lead to apoptosis of effector T cells." (PMID 37567938, 2023). "In contrast, galectin-9 overexpression in isolated tumour-infiltrating lymphocytes (TILs) at a tumour site represents T-cell exhaustion and impairment in NK cells." (PMID 37371482, 2023). "HAVCR2 inhibits anti-tumor immunity by interacting with its ligand Galectin 9 (Gal9), phosphatidylserine (Ptdser) high mobility group box 1 (HMGB1), and carcinoembryonic antigen-related cell adhesion molecule 1 (CEACAM1)." (PMID 37005667, 2023). "Galectin-9 has been detected on a variety of cancers and its secretion from human tumor cell lines can be induced by T lymphocytes, attenuating their function." (PMID 37174080, 2023). "Blockade of the tumor secretory exosome LGALS9 in a mouse GBM tumor model significantly promoted DCs antigen presentation activity and durable antitumor immunity." (PMID 37170647, 2023). "It was proposed that the blockade of galectin-9-mediated Tim3 signaling is effective to impair glioma progression by inhibiting macrophage M2 polarization and tumor angiogenesis." (PMID 36873388, 2023). "Galectin-9 expression is distributed in various tumor organs, including the liver, small intestine, thymus, kidney, spleen, lung, heart, skeletal muscle, brain, placenta, pancreas, prostate, and colon." (PMID 37047155, 2023). "In TC, we are the first to show that tumor-associated mast cells exhibit a strong inhibitory role on CD8+ T-cell proliferation and granzyme-B secretion in a galectin-9-dependent manner." (PMID 37042867, 2023). "These functions of galectin-9 are involved in apoptosis, adhesion, migration, tumor growth, invasion, and metastasis during cancer development." (PMID 37047155, 2023). "LGALS9 is then heavily expressed at the very early metaplastic stage in PanIN1, suggesting a key function in tumor progression." (PMID 38098486, 2023). "Indeed, we thought that LGALS9 could be directly implicated in tumor promotion and ADM." (PMID 38098486, 2023). "Collectively, these results showed that tumor-infiltrating mast cells suppressed CD8+ T-cell antitumor immunity through galectin-9 in TC." (PMID 37042867, 2023). "Compared with pDCs in PBMCs, tumor-infiltrating pDCs tend to use LGALS9 to affect other cell types by binding HAVCR2." (PMID 37817484, 2023). "In the mouse models of triple-negative breast cancer, 4-1BB, a galectin-9-neutralizing antibody in combination with an agonist antibody to the tumor necrosis factor receptor (TNFR) synergistically inhibited tumor growth and prolonged mouse survival." (PMID 36873388, 2023). "Our study showed that galectin-9 inhibited cell proliferation and tumor growth of PDAC cells in vitro." (PMID 37047155, 2023). "C5AR1-RPS19, LGALS9-HAVCR2, and SPP1-PTGER4 between macrophages and CD8+ T cells, associated with CD8+ T-cell dysfunction, immunosuppressive status, and tumor advanced progression, were revealed in subTME-IS." (PMID 38002057, 2023). "Multiple studies have shown a multi-faceted role for galectin-9 that contributes to tumorigenesis via tumor cell transformation, cell cycle regulation, angiogenesis, and cell adhesion." (PMID 36768365, 2023). "Galectin-9 regulates anti-tumor immunity through modulating Tim-3/galectin-9, PD-1/PD-L1, and dectin-associated immune checkpoints." (PMID 36873388, 2023). "With the development of immunotherapy, galectin-9 has emerged as a target to regulate tumor immune responses." (PMID 37047155, 2023). "In pancreatic adenocarcinoma, the expression of galectin-9 is positively correlated with PD-L1 in tumour tissues." (PMID 37371482, 2023). "In EAC cell lines, galectin-9 treatment dose-dependently inhibited tumor cell proliferation and at the same time induced caspase-independent apoptosis." (PMID 36497271, 2022).
tumor (continued). "In this study, we investigated the basic functions of galectin-9 and studied the relationship between galectin-9 and a variety of tumor-infiltrating immune cells as well as tumor immunity status via comprehensive bioinformatics analyses." (PMID 36527024, 2022). "Such is the case of two antibodies (clones 292-13 and 292-18A) reacting with high affinity with the N-CRD of human galectin-9; their use protects T cells from galectin-9 mediated cell death and promotes tumor-cell killing by T cells." (PMID 36703969, 2022). "Galectin-9 was expressed by a small proportion of tumor and myeloid cells, with a trend toward higher expression in tumor cells due to the existence of two tumors overexpressing this molecule (5.1% vs. 2.3%, p = 0.0534)." (PMID 36077799, 2022). "Dectin-1 recognizes β-1,3-glucans expressed by a broad range of fungal pathogens and bacteria, and also endogenous factors such as galectin-9 or N-glycans on tumor cells." (PMID 36353633, 2022). "Disruption of the Dectin 1-galectin 9 axis reprogrammed efficient T-cell mediated anti-tumor immunity." (PMID 36353633, 2022). "Galectin-9 was first isolated from mouse embryonic kidney tissue in 1997 and was cloned from the tumor tissue of nodular sclerosing Hodgkin’s lymphoma." (PMID 35677161, 2022). "Galectin-9 (Gal-9) has been described as a protein with many roles in tumor development and as a prognostic factor in different entities of cancer." (PMID 35377045, 2022). "Galectin-9 was highly expressed in tumor tissues of patients with pancreatic ductal adenocarcinoma (PDAC)." (PMID 36313380, 2022). "The analysis of NSCLC tumor material revealed the expression of galectin-9 by both tumor cells and TILs." (PMID 36140182, 2022). "It has been assumed that the Tim-3-Galectin-9 pathway plays an important role in regulating tumor cells escaping from immune surveillance." (PMID 35280800, 2022). "In our previous and current research, both the galectin-9 mRNA and protein expression were significantly decreased when comparing tumor tissue with normal mucosa." (PMID 36527024, 2022). "At present, there is much evidence that in a variety of tumors, TDE can damage the function of immune cells (including T cells, NK cells, and dendritic cells) by enriching protein molecules such as galectin-9 and TGFβ and then inducing tumor immunosuppression." (PMID 35565418, 2022). "Among the genes involved in the significant interactions, GAS6 and LGALS9 were expressed at higher levels in C4 than in the other tumor clusters." (PMID 35892844, 2022). "Galectin-9, which is encoded by the LGALS9 gene, can have a positive effect on the apoptosis of tumor cells." (PMID 36199574, 2022). "At the same time, since galectin-9 hampers tumor growth it is difficult to reconcile galectin-9 induction of CXCL8 with poor prognosis." (PMID 36497271, 2022). "In MIBC, a higher percentage of galectin 9-positive (Gal-9+) TAMs, a subtype of macrophages, was related to poorer prognosis accompanied by higher tumor stage and grade." (PMID 36531246, 2022). "Although the expression of LGALS9 on tumor samples was higher as well, the spearman’s correlation test showed there was no statistical correlation between STK10 and LGALS9." (PMID 35501867, 2022). "In ATL/ATLL, increased plasma galectin-9 level indicates the tumor burden and reflects opportunistic infections resembling the immune reconstitution inflammatory syndrome due to mogamulizumab therapy." (PMID 35677161, 2022). "We found a relationship between LGALS9 gene expression both with the degree of tumor differentiation and Lauren type." (PMID 36430322, 2022). "Signature B expression in malignant cells correlated with an active metabolic feature, a decrease in immune cell infiltration and an increase in the immune checkpoint expression on tumor cells (e.g., PD-L1 and Galectin-9)." (PMID 35884522, 2022).
tumor (continued). "Galectin-9 both promotes and inhibits tumor activity, depending on its interactions with its ligands on T cells, antigen-presenting cells or tumor cells, the experimental conditions, and the balance of immunity in specific TMEs." (PMID 36527024, 2022). "PD-L1 and galectin-9 (membrane and cytoplasmic staining) were highly expressed by tumor cells in more than 75% of CRCs (score 3)." (PMID 36077799, 2022). "Galectin-9 is a member of the galectin family and has been reported to have a tumor-promoting or antitumor effect in response to the immune microenvironment." (PMID 36527024, 2022). "Galectin-9 siRNA-mediated immunotherapy elicited anti-tumor immunity through tumor-suppressive macrophage polarization, cytotoxic T lymphocytes recruitment, and regulatory T cells downregulation." (PMID 35292030, 2022). "We also validated the significant relationship between galectin-9 expression and the previously established DC and T-cell activation-related factors, antigen-presenting cells, tumor infiltrating lymphocytes, and DC markers (CD208 as mDC and CD1a as imDC)." (PMID 36527024, 2022). "Further analysis showed that ligand-receptor pairs, including MIF − (CD74 + CXCR4), MIF − (CD74 + CD44), MDK–NCL and LGALS9 − CD45, etc. mediated the communication between m6A associated subtypes of TME cells and tumor epithelial cells." (PMID 35509079, 2022). "Galectin-9 helps tumor cells accomplish immune evasion by interacting with TIM-3 expressing Th1 cells and promotes their apoptosis." (PMID 36428567, 2022). "Galectin-9 is produced by diverse cell types, including tumor cells, endothelial cells and lymphocytes, and interacts with Tim-3 to negatively regulate cellular immune responses." (PMID 35464400, 2022). "We found that SLC1A5 and SPP1 are mainly produced by tumor cells while LGALS9 and PTGER4 are mainly expressed in TAMs." (PMID 36476645, 2022). "And we also found that tumor and myeloid cells with stronger expression of LGALS9 in the high PRGScore group in the single cell dataset." (PMID 35479097, 2022). "ROC analysis revealed that the expression of the IDO1 (p = 0.025) and LGALS9 (p = 0.024) genes had a statistically significant relationship with the degree of tumor differentiation." (PMID 36430322, 2022). "Galectin-9 expression in NSCLC is found to be a favorable prognostic marker due to interactions between tumor-infiltrating lymphocytes and tumor cells." (PMID 35681762, 2022). "Mechanistically, tumor-secreting Gal-1 reprograms the tumor endothelium to upregulate cell-surface programmed death-ligand 1 (PD-L1) and galectin-9, resulting in the inhibition of T cell infiltration." (PMID 34680031, 2021). "Tumor-infiltrating T cells showed upregulation of galectin-9 compared to T cells from matched blood." (PMID 33803936, 2021). "A large number of studies have shown that the activation of LGALS9-HARVCR2 in various tumor tissues is related to the development of tumors and negatively regulation of immune signaling." (PMID 35127731, 2021). "In contrast, B7H3, IDO-1 and Galectin-9 positivity on tumor cells was only seen in 21.0% (19/92) of cases, although their expression was predominantly positive in the stromal area." (PMID 35145510, 2021). "Compared to the normal tissue N1, all the PDXs, Org2, and the primary tumor showed a reduction of transcript abundance of the major histocompatibility complex (HLA-A and HLA-B) and of galectin-9, the main ligand of the inhibitory receptor Tim-3." (PMID 33602919, 2021). "The activation of the LGALS9-HAVCR2 signal can co-express with PD-1 in tumor-infiltrating immune cells, and cooperate to mediate effector T cell exhaustion and dysfunction." (PMID 35127731, 2021). "TIM-3 is expressed on Th1 cells, and its interaction with its ligand Galectin-9 (Gal-9) on tumor cells inhibits Th1 cell responses." (PMID 34447383, 2021).
tumor (continued). "Sarcoma data from the TCGA were downloaded to analyze the lncRNAs positively correlated with immune checkpoint inhibitory molecules (CD274, CD80, CD86, PDCD1 LG2 and LGALS9), which accelerate the process of tumor cell immune evasion." (PMID 34178688, 2021). "TIM-3 was mainly expressed by tumor cells, TAMs, and small lymphocytes, whereas galectin-9 was mainly expressed by TAMs, ECs, glial cells, and gemistocytes." (PMID 33664848, 2021). "Few studies have reported on TIM-3 in exosomes, despite the existence of various studies based on tumor tissues or TILs to reveal the important role of TIM-3/Galectin-9 signaling in tumors." (PMID 34743730, 2021). "During activation of anti-tumor-specific responses, exogenous galectin-9 modulates antigen presentation, promoting the differentiation of plasmacytoid dendritic-like cells, dendritic cell maturation, and a Th1 polarizing microenvironment." (PMID 34572756, 2021). "Our findings demonstrate that lactate produced by PKM2 upregulation promotes tumor progression and Galectin-9-mediated immunosuppression via NF-κB signaling inhibition in HNSCC, which bridges metabolism and immunosuppression." (PMID 34290225, 2021). "We confirmed that transcutaneous CO2 application to a mouse model, in which an SCC was transplanted, reduced tumour immunosuppressive factors such as PD-L1, PD-L2, and galectin-9." (PMID 34307656, 2021). "While the anti-tumor effect of galectin-9 was demonstrated in several experimental models, other strategies demonstrated galectin-9 has apparent diametrical opposite roles in immune regulation." (PMID 34572756, 2021). "The binding of TIM3 to its ligand galectin 9 (LGALS9) induces the depletion of T cells, which cannot be activated and are unable to secrete cytokines, leading to tumor immunosuppression and immune evasion." (PMID 34123852, 2021). "Galectin-9 subsequently displays immunosuppressive activities on cytotoxic and helper T cells in the tumour microenvironment as well as on NK cells." (PMID 34234778, 2021). "The average QIF scores of PD-L1, HHLA2, B7H3, IDO-1 and Galectin-9 were significantly higher in the stromal compartment than in the tumor subregion." (PMID 35145510, 2021). "In summary, this study demonstrated that oncogenic PKM2 drive tumor progression and Galectin-9-mediated immunosuppression by lactate production." (PMID 34290225, 2021). "On the contrary, in head and neck squamous cell carcinoma, GCN5 acetylates H3K27, which activates transcription of PD-L1 and galectin-9 to evade tumor immunity." (PMID 34880761, 2021). "Further studies in a mouse model of HNSCC, showed that this lectin generates an immunosuppressive barrier that prevents T cell migration to the tumor, particularly by up-regulation of immune-inhibitory ligands including PD-L1 and Galectin-9 (Gal-9)." (PMID 33804419, 2021). "Not only do tumor cells express galectin-9, but this protein is also detected in tumor-infiltrating Tregs and tumor-associated macrophages." (PMID 34572756, 2021). "After administration twice a week for a total of 4 times, tumours were collected and the expression of tumour immunosuppressive factors (PD-L1, PD-L2, and galectin-9) was evaluated using real-time polymerase chain reaction and immunostaining." (PMID 34307656, 2021). "In the immune checkpoint module, we found that an increase in ferroptosis tendency score would lead to a specific interaction of LGALS9-HARVCR2 between tumor cells and immune cells, with more activation in the double-high group than in the single-high." (PMID 35127731, 2021). "TIM-3 is a negative regulator of cytotoxic and helper T cells and can promote the formation of a suppressive tumor microenvironment through the TIM-3–galectin-9 pathway." (PMID 33864445, 2021). "In fact, we demonstrate that the TIM3 ligands galectin 9, PtdSer, and CEACAM1 tend to be linked to tumor grade; analysis of GlioVis data showed that their expression was highest in GBM." (PMID 33800561, 2021).
tumor (continued). "TIM-3 can bind several ligands commonly found in the tumor microenvironment, including galectin-9 (Gal-9), HMGB-1, phosphatidylserine (PtdSer), and cell adhesion molecule 1 (Ceacam-1)." (PMID 34572874, 2021). "Co-delivery of galectin-9 siRNA and the immunogenic chemotherapy oxaliplatin by exosomes elicited successful tumor control via immune activation." (PMID 34683931, 2021). "HAVCR2 (TIM3) of NK interacts with Galectin-9 on tumor cells, dysfunctional CD8 cells, macrophages and dendritic cells in NPC." (PMID 33671917, 2021). "Galectin-9 on tumor cells is considered the major ligand for TIM-3 and induces T lymphocyte exhaustion or apoptosis and regulation of NK cell function." (PMID 31907020, 2020). "The effect of galectin-9 on tumor cells is dependent upon its ligand, T-cell immunoglobulin and mucin-domain containing-3 (Tim-3)." (PMID 32033052, 2020). "Tumor-infiltrating immune cells generally displayed greater cell-surface expression of galectin-9 compared with immune cells from matched blood." (PMID 32055023, 2020). "In contrast, galectin-9 expression was high in most cases and not only present on tumor cells, but also on some intratumoral leukocytes." (PMID 32055023, 2020). "Blockade of the galectin-9/dectin-1 axis enhanced intratumoral T-cell activation and resulted in substantial tumor regression and extended survival." (PMID 32055023, 2020). "Galectin-9 was reported to be related to different aspects of tumor growth, metastasis, immunosuppression, and immunomodulation." (PMID 33381555, 2020). "Immune checkpoint molecules, including PD-L1/2, B7-1/2, B7-H3, B7x, VISTA, and Galectin-9, have been characterized as potent regulators of immune activation, and play a crucial role in the mechanisms that mediate tumor immune escape." (PMID 32934224, 2020). "TIM3 promotes tumor survival by binding to galectin-9 (Gal9) on tumor cells and inducing T cell exhaustion." (PMID 32733369, 2020). "Using flow cytometry, we determined galectin-9 expression on immune cells from tumor and matched blood samples from 12 patients with resectable PDAC." (PMID 32055023, 2020). "H3K27 acetylation activated the expression of two immune checkpoint molecules, PD-L1 and galectin-9, on tumor cells." (PMID 31907020, 2020). "Galectin-9, together with Tim-3, can be shed from the cell surface by proteolytic enzymes, thus being released into the tumour microenvironment or blood." (PMID 33295886, 2020). "The Lgals9-based network by Cytoscape showed extensive and complex correlation between Lgals9 and other molecules in tumor-immune microenvironment, including CD4, CD19, CD79A, CIS, IL2RG, FCGR2C, and FASLG." (PMID 33082168, 2020). "Tumor cells also express galectin-9 which interacts with TIM-3 on tumor-infiltrating DCs regulating their function." (PMID 32656079, 2020). "Galectin-9 was present in the cytoplasm and also nuclei of tumor cells as demonstrated by confocal microscopy." (PMID 32055023, 2020). "This interplay between tumor cells and tumor-infiltrating DCs is probably pivotal for the development and perpetuation of other types of malignancies, since galectin-9 is highly expressed by several tumor cell types." (PMID 32656079, 2020). "The frequency of galectin-9+TAMs predicted poor overall survival and recurrence-free survival, is correlated with tumor stage and grade in bladder cancer patients." (PMID 32508809, 2020). "Subsequently, galectin-9 ligation by macrophages increased M2-polarization and tumor progression due to an immunosuppressive tumor microenvironment." (PMID 32055023, 2020). "In the CSF of GL-261 WT tumor-bearing mice, more than 60% of DCs highly expressed LGALS9, while LGALS9hi DCs in GL-261 LGALS9−/− tumor-bearing mice accounted for less than 5% of the total DC population." (PMID 33093453, 2020). "On day 14, the spleen of GL-261 LGALS9−/− tumor-bearing mice was significantly larger than that of GL-261 WT tumor-bearing mice." (PMID 33093453, 2020).